HMGB1 (high mobility group box 1)
Diseases named in the same sentence as HMGB1 in open-access papers (continued):
Sharing a sentence is not in itself a finding about the gene and the disease.
tumor (continued). "This suggests the possibility of activating the immunogenicity of ferroptotic tumor cells by manipulating the pattern of HMGB1 release." (PMID 38593415, 2024). "Extracellular HMGB1 due to tumor cell death can induce autophagy, with RAGE receptors playing a central role in HMGB1-induced autophagy." (PMID 38725632, 2024). "HMGB1 acts as a tumor promoter outside the cell and modulates inflammation through the RAGE and TLR pathways, whereas intracellularly binding to DNA to maintain nuclear integrity." (PMID 39830522, 2024). "Collectively, Lf-GL conjugate was delivered to GBM, and it effectively regulated the tumorigenic activity of HMGB1 in the tumor microenvironment." (PMID 37210579, 2023). "Extracellular HMGB1 promotes invasion and metastasis by stimulating cell migration and by mediating interactions among components of the extracellular matrix and the tumor microenvironment." (PMID 37759736, 2023). "In mouse thymoma cells (EG7), CPA can induce immunogenic tumor cell apoptosis and release of large amounts of HMGB1." (PMID 37153795, 2023). "At this point, Lf-GL, which has a high binding affinity for HMGB1, eliminate the activity involved in tumor development and metastasis by arresting HMGB1." (PMID 37210579, 2023). "PT increased tumor cell death associated with increased DNA damage, and IL6 and HMGB1 expression compared with sham irradiation." (PMID 36672266, 2023). "It was then found that HMGB1 played a crucial role in the impetus of the pro-tumor activation of neutrophils." (PMID 35066729, 2023). "To clarify the influence of tumor released-HMGB1 on endothelial cell proliferation, we mimicked the tumor microenvironment with a co-culture system using 0.4 μm pore size trans-well plates." (PMID 37210579, 2023). "In this study, we provide the first example of naphplatin deterring platinum-containing chemotherapy immune evasion and cancer metastases via resetting HMGB1-mediated lysosomal function of tumour cells and macrophages." (PMID 37537587, 2023). "High-mobility group box-1 (HMGB1) released from the tumor microenvironment plays a pivotal role in the tumor progression." (PMID 37210579, 2023). "The tumor volume significantly decreased in the mice injected with 3-OBA or HMGB1 inhibitor (RAP + EP) compared with the control group." (PMID 36709284, 2023). "Treatment of mice with renal cell tumors with antibody to HMGB1 similarly reduces tumor growth and MDSC levels." (PMID 36831371, 2023). "RT induced an increased proportion of HMGB1+ tumor cells and upregulation of HMGB1 and STING protein expression in the TME, favoring the maturation of DCs." (PMID 37833255, 2023). "At the endpoint, the levels of Ki67, p-H2AX, cleaved-caspase 3, cleaved-PARP, p-JNK, CV-B5/F, and HMGB1 were further examined in subcutaneous xenograft tumor sections by IHC." (PMID 37743418, 2023). "We reported that histotripsy induces the early release of immunogenically intact tumor antigens and pro-inflammatory damage-associated molecular patterns (DAMPs) like high mobility group box protein 1 (HMGB1) within the tumor ablation zone." (PMID 36756111, 2023). "RAGE exhibits potent interplay with HMGB1, augmenting cell motility and thereby promoting tumour invasiveness." (PMID 37970208, 2023). "As mentioned in the manuscript, HMGB1 is a pro-tumorigenic factor that can promote tumor growth, angiogenesis, and inflammation." (PMID 37210579, 2023). "We found that F1,6P is an allosteric ligand of the chromosome structural protein HMGB1 and behaves as a potential and promising anti‐tumor drug." (PMID 36642839, 2023). "By arresting tumor secreted-HMGB1, GL, Lf and Lf-GL reduced endothelial cell proliferation by 10.7 ± 2.9, 8.2 ± 2.9 and 13.0 ± 0.7%, respectively, and HMGB1 level decreased to 190.7 ± 19.0, 177.3 ± 3.6 and 176.1 ± 4.9 ng mL−1, respectively." (PMID 37210579, 2023). "Glycyrrhizin (GL) is an effective intracellular antagonist of tumor released HMGB1, but its pharmacokinetics (PK) and delivery to tumor site is deficient." (PMID 37210579, 2023).
tumor (continued). "HMGB1 mediates tumor immune suppression by recruiting MDSCs, activating regulatory T cells, and inhibiting dendritic cell infiltration." (PMID 37238964, 2023). "It is important to arrest HMGB1 in terms of tumor malignancy because extracellular HMGB1 is known to bind RAGE, which is overexpressed in high grade tumors." (PMID 37210579, 2023). "The transcription of S100s and HMGB1 in tumors is a very well-orchestrated process that integrates multiple signals from all cells present in the tumor." (PMID 37627239, 2023). "Most studies are consistent with the concept that extracellular HMGB1 acting via RAGE promotes tumor progression." (PMID 36831371, 2023). "Tumor-infiltrating dendritic cells (DC) highly express TIM3, which can compete with nucleic acid binding to its ligand high-mobility group protein B1 (HMGB1), reducing anti-tumor immunity otherwise mediated by nucleic acids." (PMID 36874131, 2023). "The high binding capability of Lf-GL to HMGB1 inhibits tumor progression cascade such as tumor angiogenesis, development, and metastasis." (PMID 37210579, 2023). "In the nucleus, HMGB1 regulates gene transcription by binding to and stabilizing DNA, and has a tumor suppressor effect." (PMID 37627239, 2023). "Glycyrrhizin sensitized cancer cells to radiation and cisplatin treatment by regulating a protein known for its involvement in tumor metastasis and proliferation, the high mobility group protein B1 (HMGB1)." (PMID 37836809, 2023). "In vitro studies with mouse tumor cells demonstrated that this process is exacerbated within hypoxic regions of the TME because activation of hypoxia inducible factor α drives the release of HMGB1 from tumor cells." (PMID 36831371, 2023). "We also measured the HMGB1 concentration in tumor tissues, and the levels of HMGB1 in mU@OMVs treated mice were significantly enhanced than those in other groups, consistent well with the plasma results." (PMID 36966130, 2023). "Defective TLR1 on DCs impaired their maturation ability by HMGB1 and reduced the secretion of IFNγ from T cells to eradicate tumor cells in vitro." (PMID 37945630, 2023). "Collectively, our study demonstrates a close association between HMGB1 and tumor progression, suggesting Lf-GL as a potential strategy for coping with DAMP-related tumor microenvironment." (PMID 37210579, 2023). "Meanwhile, Lipo-Ce6/TPZ@MH decoys maintain binding interactions with high levels of HMGB1 to prevent platelet-mediated tumor metastasis." (PMID 37168380, 2023). "Based on these results, it appears that HMGB1 released by dead tumor cells promotes chemical resistance as well as tumor development through RAGE-dependent ERK/Drp1 phosphorylation." (PMID 37669960, 2023). "A more recent study in Iranian patients with OSCC showed that HMGB1 detection in the blood as well as in the neoplastic tissues of OSCC patients was highly correlated with tumor size and lymph node involvement." (PMID 37511951, 2023). "HMGB1 has also been detected in tumor-cell-derived exosomes, which in combination with extracellular HMGB1 enhance cancer cell survival." (PMID 36831371, 2023). "The programmable triple oxidative stress of Tf@IR820‐DHA induced the upregulation of CRT and HMGB1 levels in tumor cells and proliferation of CTLs to activate significantly antitumor immune response." (PMID 36437106, 2023). "Then, the expression levels of HMGB1, drug-resistant proteins, apoptosis marker proteins, and proliferation marker protein in tumor tissues were also analyzed using IHC." (PMID 37518006, 2023). "Using Pearson’s correlation (R) analysis to estimate correlation strengths between S100s and HMGB1, we observed significantly more and stronger correlations within tumor samples than within cell lines." (PMID 37627239, 2023). "PI3K/AKT axis has an essential role in tumor progression, and HMGB1 has been shown to encourage angiogenesis and migration of tumors through PI3K/AKT signalling." (PMID 36926585, 2023).
tumor (continued). "The levels of “find me” signals ATP and HMGB1 in the supernatant of treated tumor cells were measured dynamically at different time points." (PMID 37684628, 2023). "We found that the Arf1‐ablated tumor cells release oxLDL, HMGB1‐gDNA complex, and also induce expression of CD36, TLR2, and TLR6 in DCs." (PMID 37786300, 2023). "High Mobility Histone 1 (HMGB1) is secreted by tumor cells, and ATP molecules are released from the cells and heat shock proteins." (PMID 37291495, 2023). "Based on the data, it can be inferred that GL, Lf, and Lf-GL have the potential to inhibit tumor angiogenesis by targeting HMGB1, which is known to be a crucial mediator of this process." (PMID 37210579, 2023). "HMGB1 released by dying tumor cells also inhibited antitumor immune responses by competing with nucleic acid binding to TIM3, a receptor expressed by intratumoral DCs." (PMID 36949244, 2023). "In this work we demonstrated that two proteins with the pronounced pro-tumor activity Hsp70 and HMGB1 form complex in cells, subjected to chemotherapy and being released to extracellular space trigger proliferation of a tiny population of cancer cells." (PMID 37880798, 2023). "In contrast, in the ASL-modulated tumors, Dox triggered a more notably elevated fluorescence intensity of CRT and HMGB1 release, likely due to both the adjuvant properties of Ausome and a heat-facilitated increase in tumor Dox perfusion." (PMID 37620331, 2023). "ICD triggers the release of damage-associated molecule patterns (DAMPs) from tumor cells, such as calreticulin (CRT), adenosine triphosphate (ATP), and high mobility group protein 1 (HMGB1), facilitating the recruitment and activation of tumor-specific CTLs." (PMID 37229252, 2023). "In this context, TIM-3 competes as a receptor for the nuclear alarmin protein high-mobility-group box 1 (HMGB1) secreted by dying tumor cells." (PMID 37928547, 2023). "Then, phosphorylated HMGB1 is transported to the cytoplasm and subsequently secreted out of the cells, where it plays a pivotal role in tumor progression." (PMID 37210579, 2023). "Meanwhile, the amount of HMGB1 in the culture medium of the Arf1‐ablated tumor cells was significantly increased." (PMID 37786300, 2023). "Among the candidates for the role of Hsp70 binders, we also considered the high mobility group B1 protein, HMGB1 and calreticulin, both known DAMPs and markers of tumor relapse after radiotherapy." (PMID 37880798, 2023). "TTFields can induce immunogenic death of tumor cells, leading to the release of danger signals such as HMGB1, ATP, and calreticulin, which activate dendritic cells and promote CD45+ leukocyte enrichment." (PMID 37916157, 2023). "It has been established that HMGB1, after anti-tumor therapy, changes its conformation and translocates from the nucleus to the cytoplasm and then into the extracellular matrix." (PMID 37880798, 2023). "Here, it is discovered that the nuclear‐accumulated F1,6P impairs cancer cell viability by directly binding to high mobility group box 1 (HMGB1), the most abundant non‐histone chromosome structural protein with paradoxical roles in tumor development." (PMID 36642839, 2023). "As a key protein that promotes tumor angiogenesis and that regulates the immune response, HMGB1 seems to be the main target by which miR-665 influences metastasis and invasion." (PMID 37894282, 2023). "More specifically, HMGB1 induces the NF-kB signaling pathway promoting tumor-related inflammation that converts the microenvironment into a permissive and favorable setting for tumor progression, inducing cell proliferation and migration." (PMID 36769076, 2023). "In A549-DDP-si-HMGB1 group, the tumor cell apoptosis level increased, the number of cell shrinkage was the largest, and the necrosis area was larger." (PMID 37518006, 2023).
tumor (continued). "With our experimental setting we have shown for the first time that the DAMP HMGB1 is only released from HPV-positive HNSCC tumor cells after fractionated irradiation and that this can be significantly enhanced with taxane-based chemotherapy." (PMID 37857049, 2023). "When tumor cells undergo ICD, they release a variety of tumor-associated antigens and damage-associated molecular patterns (DAMPs), such as high mobility group protein 1 (HMGB1), calreticulin (CRT), adenosine-triphosphate (ATP) and heat shock protein (HSP90α)." (PMID 38106403, 2023). "In non-tumor diseases, HMGB1 triggers inflammation as a damage-related molecular model, and its pro-inflammatory effect is closely related to its release to the extracellular environment." (PMID 36869074, 2023). "Studies in tumor cells show that HMGB1 can induce autophagy in different compartments, including the nucleus, cytoplasm, and extracellular fluid." (PMID 36658496, 2023). "HMGB1 is a highly chemoattractant molecule, leading Tregs to the tumor site and suppressing their T-cell proliferative activity, thus promoting a tumor-escape environment in HNSCC patients, including OSCC patients." (PMID 37511951, 2023). "The CD36/TLR2/TLR6 form a coreceptors complex on DC surface, and the exogenous ligands of tumor‐derived oxLDL and HMGB1‐gDNA complex join the coreceptors complex through binding CD36 and TLR2/TLR6, respectively." (PMID 37786300, 2023). "These inflammatory factors include pro-inflammatory cytokines IL-1β, IL-18, and DAMPs such as ATP, DNA, or HMGB1, and in doing so they regulate the proportions of tumor-infiltrating immune cells such as T cells, NK cells, DCs, monocytes, and MDSCs." (PMID 36831197, 2023). "Other signalling molecules that are secreted by HCC tumour cells include the protein high mobility group box 1 (HMGB1), which promotes autophagy-regulated M2 polarization of TAMs via the production of ROS in these cells through the TLR2/NOX2 axis." (PMID 37894344, 2023). "We have previously shown that HMGB1 secreted from tumor cells infected with oHSV increases vascular leakage and edema, but administration of an HMGB1-blocking antibody inhibits this effect." (PMID 36789106, 2023). "Combined inhibition of RAGE and HMGB1 was found to have a stronger anti-tumor effect than either RAGE or HMGB1 inhibition alone, suggesting that both RAGE and HMGB1 can affect tumorigenesis independent of each other." (PMID 36789106, 2023). "Here, the effects of single agent chemotherapies and their combination as part of the FLOT, CROSS CT and MAGIC chemotherapy regimens on immunogenicity of OGJ tumours were assessed through expression of HMGB1, CRT, MIC-A/B and HLA-DR." (PMID 35986757, 2023). "It has been shown in tumor cells that ROS promote the transport of HMGB1 from the nucleus to the cytoplasm, while cytoplasmic HMGB1 interacts with Beclin-1, which, in turn, is released from the Beclin-1/Bcl-2 complex and induces autophagy." (PMID 37158301, 2023). "DCs infiltrated in tumor enhance expression of T cell immunoglobulin mucin receptor 3 (TIM3) which sequesters high mobility group protein B1 (HMGB1), resulting in impairment of DC activation and antigen presentation." (PMID 37064113, 2023). "A survey of immune checkpoint receptor ligands revealed upregulation of Lgals3 in fibroblasts, Hmgb1 in tumor cells, and Lgals9 and Cd274 across cell clusters." (PMID 38304252, 2023). "Although tumor cells mainly express reduced-HMGB1, infiltrating leukocytes are responsible for the presence of oxidized-HMGB1 in tumor microenvironment." (PMID 37251376, 2023). "The effects of other intercellular substances in the tumour microenvironment, such as ATP, HMGB1, IL1β, and LDH, are still uncertain." (PMID 37211606, 2023). "The ROS enriched tumour micro-milieu favours the oxidation of HMGB1, besides other proteins, lipids and DNA, thereby facilitating the undesirable effects of this protein on immune suppression and cancer progression." (PMID 37970208, 2023).
tumor (continued). "The polarization of macrophages, along with the additional release of cytokines and the general formation of an immunosuppressive tumor microenvironment, indicates HMGB1 protein as an important target for OSCC immunotherapy." (PMID 37511951, 2023). "Lf-GL targets GBM through interaction with LfR and allows to arrest HMGB1 released from the tumor microenvironment." (PMID 37210579, 2023). "The tumor microenvironment plays an important role in promoting an aggressive phenotype through hypoxia and the secretion of HMGB1 and other factors." (PMID 36769076, 2023). "This article reviews the involvement of RAGE, S100A8/A9, and HMGB1 in tumor progression and how these molecules impact MDSC development, half-life, and function." (PMID 36831371, 2023). "In order to evaluate the induction of ICD of tumor cells by Cu-based hydrogel, classical damage-associated molecular patterns (DAMPs), including CRT, HMGB1 and the release of ATP were investigated in 4T1 cells." (PMID 37165428, 2023). "Due to the hypoxic conditions in tumor, tumor cells express more neutrophil-associated chemokines (CXCL1, CXCL2, and CXCL5) and HMGB1 to rapidly recruit neutrophils." (PMID 38023616, 2023). "Radiation-induced cell death can cause dying cancer cells to elicit danger-associated molecular patterns (DAMPs), such as calreticulin translocation to the tumor cell surface and the extracellular secretion of ATP and high-mobility group box 1 (HMGB1)." (PMID 37408232, 2023). "They find that the Arf1‐ablated tumor cells release OxLDL, HMGB1, and genomic DNA, which together bound to a coreceptor complex of CD36/TLR2/TLR6 on DC surface." (PMID 37786300, 2023). "The resulting PMN-MDSCs induce the formation of neutrophil extracellular traps (NETs), which in conjunction with tumor-cell-released HMGB1 increase lung metastases." (PMID 36831371, 2023). "This tumor-specific cytoplasmic expression of HMGB1 confers immune tolerance and poor prognostic value, by serving as a tolerogenic signal in RAGE—reliant manner in extracellular oxidised form." (PMID 37970208, 2023). "The impact of RAGE and its principal ligands S100A8/A9 and HMGB1 on multiple aspects of tumor progression has been established in numerous and diverse mouse and human cancers." (PMID 36831371, 2023). "We also detected higher serum and tumor homogenate levels of HMGB1 in the KH3 monotherapy and combined groups." (PMID 37705495, 2023). "HMGB1 is actively secreted by endothelial cells, immune cells, neurons, platelets, astrocytes, and tumor cells during stress conditions, or secondary to other DAMP danger signals as support." (PMID 37626858, 2023). "Extracellular HMGB1 can activate immune cells, including microglia, and promote tumor invasiveness, resistance, and immunosuppression." (PMID 38132142, 2023). "It is also important to note that our study only gives a snapshot of the levels of S100 and HMGB1 transcripts in the cancer cells in standard cell culture growth conditions and that cancer cells’ growth conditions are very different in the tumor environment." (PMID 37627239, 2023). "Our results implied that HMGB1 overexpression promoted the drug resistance but suppressed the tumor cell apoptosis in NSCLC xenograft model." (PMID 37518006, 2023). "HMGB1 has been found to be secreted from tumor cells, which also mediated anti-tumor immune responses via activating Toll-like receptor 2 + 4 signaling." (PMID 37174080, 2023). "This is in accordance with other studies, were HMGB1 was suggested as a possible key promoter of tumor progression and infiltration of the mandible bone or the upper jaw in OSCC." (PMID 37046731, 2023). "The higher calreticulin (CRT) exposure and release of high mobility group box 1 (HMGB-1) also act as an “eat-me” signal to induce tumor cell apoptosis." (PMID 37238966, 2023).